ZFYVE26 (zinc finger FYVE-type containing 26)
Description:
Phosphatidylinositol 3-phosphate-binding protein required for the abscission step in cytokinesis: recruited to the midbody during cytokinesis and acts as a regulator of abscission. May also be required for efficient homologous recombination DNA double-strand break repair.
Synonyms: FYVE-CENT; KIAA0321; SPG15
Tractability: PROTAC: ubiquitination databases record sites on it; its protein half-life has been measured.
Gene: Protein-coding gene on chromosome 14 (67,727,374 to 67,816,590, reverse strand). Ensembl gene ENSG00000072121.
Subcellular location: Cytoplasm, cytoskeleton, microtubule organizing center, centrosome; Midbody
Gene Ontology:
Molecular function: identical protein binding; phosphatidylinositol-3-phosphate binding; protein binding; protein kinase binding; metal ion binding
Biological process: autophagosome organization; double-strand break repair via homologous recombination; lysosome organization; regulation of cytokinesis; lysosomal membrane organization; membrane bending; mitotic cytokinesis
Cellular component: centrosome; early endosome; late endosome; lysosomal membrane; lysosome; midbody
Genetic constraint (gnomAD): Loss-of-function variants: 181 observed, 290.76 expected, observed/expected ratio (o/e) 0.62, 90% interval 0.55 to 0.7. The upper end of that interval is the gene's LOEUF score, 0.7, which puts it in group 2 of 6, group 1 being the genes least tolerant of losing a copy. Missense variants: 2,821 observed, 3,265.9 expected, observed/expected ratio (o/e) 0.86, 90% interval 0.84 to 0.89. Synonymous variants: 1,129 observed, 1,274.1 expected, observed/expected ratio (o/e) 0.89, 90% interval 0.84 to 0.93.
Homologues: Orthologues: chimpanzee ZFYVE26 (98% identical), macaque ZFYVE26 (98% identical), pig ZFYVE26 (88% identical), rabbit ZFYVE26 (87% identical), dog ZFYVE26 (86% identical), guinea pig ZFYVE26 (85% identical), mouse Zfyve26 (82% identical), rat Zfyve26 (82% identical), tropical clawed frog zfyve26 (51% identical), zebrafish zfyve26 (45% identical), Drosophila melanogaster CG6051 (4% identical), Drosophila melanogaster CG31064 (4% identical), and 1 more. Paralogues in human: ZFYVE16 (9% identical), RUFY1 (5% identical), RUFY2 (5% identical), ZFYVE28 (5% identical), PLEKHM2 (5% identical), ZFYVE1 (5% identical), RUFY3 (4% identical), SNX29 (4% identical), ZFYVE19 (3% identical), RUNDC3B (3% identical), RUNDC3A (3% identical), PLEKHF1 (3% identical), and 1 more.
Diseases named in the same sentence as ZFYVE26 in open-access papers:
ZFYVE26 is named in the same sentence as 56 diseases in open-access papers, as found by Europe PMC text mining. Sharing a sentence is not in itself a finding about the gene and the disease. The quoted sentences say what the papers report.
hereditary spastic paraplegia (18 papers, 2010 to 2025). Hereditary spastic paraplegias (HSP) comprise a genetically and clinically heterogeneous group of neurodegenerative disorders characterized by progressive spasticity and hyperreflexia of the lower limbs. "To date, more than 82 gene loci have been found to cause HSP, and SPG15 (ZFYVE26) is one of the most common autosomal recessive hereditary spastic paraplegias (ARHSPs) with a thin corpus callosum (TCC), presents with early cognitive impairment and slowly progressive leg weakness." (PMID 37681008, 2023). "ZFYVE26 and SPG11, the gene products of ZFYVE26 and SPG11 implicated in two forms of hereditary spastic paraplegia, respectively, form a complex targeted to the lysosome and are also probably functionally closely related." (PMID 34130600, 2022). "Mutations in the spastic paraplegia genes SPG11, encoding spatacsin, and ZFYVE26, encoding Spastizin (SPG15), cause the most prevalent forms of autosomal-recessive hereditary spastic paraplegia with thinning of the corpus callosum (AR-HSP-TCC)." (PMID 33498913, 2021).
Cognitive impairment (8 papers, 2015 to 2025). Abnormal cognition is characterized by deficits in thinking, reasoning, or remembering. "70% of complex HSP patients presenting with progressive spasticity, intellectual impairment and thin corpus callosum are accounted for by mutations in SPG11/spatacsin and ZFYVE26/spastizin, both having roles in autophagosome maturation and endolysosomal function." (PMID 31142229, 2020). "For example, mental retardation in SPG15/ZFYVE26 and SPG46/GBA2, cognitive impairment and epilepsy in SPG35/FA2H and SPG84/PI4KA." (PMID 39932116, 2025).
Spastic paraplegia (7 papers, 2013 to 2025). Complete loss of the ability to move the lower limbs accompanied by spasticity of the lower limbs. "Lastly, mutations in two genes called protrudin (ZFYVE27) and spastizin (ZFYVE26), which encode FYVE domain-containing proteins, cause subtypes of spastic paraplegia (MIM 610244 and MIM 270700, respectively)." (PMID 31413155, 2019). "Zfyve26 knockout mice do not show developmental defects but develop late-onset spastic paraplegia with cerebellar ataxia confirming that SPG15 is caused by ZFYVE26 deficiency." (PMID 24367272, 2013). "We identified two cases of spastic paraplegia (SPG), specifically SPG15 (ZFYVE26) and SPG7 (SPG7), with SPG15 showing a bigger and broader phenotypic onslaught compared to SPG7 in the form of seizures, hearing loss, and cerebellar atrophy." (PMID 32999401, 2020).
Ataxia (5 papers, 2013 to 2024). Ataxia refers to impaired coordination of voluntary muscle movement. "Here we demonstrate that Zfyve26-deficient mice develop a progressive gait disorder starting at 12 months of age, which is further complicated by bladder dysfunction and ataxia." (PMID 24367272, 2013). "SPG15 is a recessively inherited HSP variant caused by mutations in the ZFYVE26 gene and is additionally characterized by cerebellar ataxia, mental decline, and progressive thinning of the corpus callosum." (PMID 24367272, 2013). "As Purkinje cells play a critical role for motor coordination, the loss of Purkinje cells at least contributes to the cerebellar ataxia phenotype observed in both Zfyve26 knockout mice and SPG15 patients." (PMID 24367272, 2013). "Pathogenic variants in COL18A1, UFSP2, ZFYVE26, and ATP13A2 contribute to a wide range of clinical phenotypes, from ASM-resistant epilepsy and developmental delay to ataxia, intellectual disability, speech impediment, and other associated symptoms." (PMID 38783254, 2024). "Our study reports the second identified case of ZFYVE26 related spinocerebellar degeneration in the Pakistani population." (PMID 37510308, 2023).
breast carcinoma (2 papers, 2011 to 2013). "The ZFYVE26 gene encoding FYVE-CENT was found mutated in breast cancer samples with a frequency of more than 10%." (PMID 21455500, 2011). "Other coding SNPs that could include causal variants producing synthetic associations (associations of rare with common SNPs of high penetrance) include SNPs in genes INS-IGF2, ZFYVE26, C16orf46, UNC13A, NRIP1 and CCDC91 for breast cancer and SNPs in SNED1 and PASK for prostate cancer." (PMID 23555315, 2013).
epilepsy (2 papers, 2024 to 2025). A brain disorder characterized by episodes of abnormally increased neuronal discharge resulting in transient episodes of sensory or motor neurological dysfunction, or psychic dysfunction. "Using WES, homozygous pathogenic variants in the COL18A1, UFSP2, ZFYVE26 and ATP13A2 genes were detected to cause ASM-resistant epilepsy and its comorbid conditions in four Pakistani families." (PMID 38783254, 2024). "Similarly, the ZFYVE26 variant p.Tyr643MetfsX2 identified in the current study is a frameshift variant resulting in a truncated protein, disrupting the normal function of the gene and, consequently, causing ASM-resistant epilepsy, spastic ataxia, DD, and ID phenotypes in patients." (PMID 38783254, 2024).
autosomal recessive spastic paraplegia (1 paper, 2014). "While ZFYVE26 has been associated with autosomal recessive spastic paraplegia in humans, the precise biological function of this gene has not yet been described." (PMID 25250046, 2014).
colorectal cancer (1 paper, 2020). A primary or metastatic malignant neoplasm that affects the colon or rectum. "Variants in the ZFYVE26 gene have been associated with colorectal cancer, variants in the MADCAM1 gene have been associated with multiple sclerosis, and variants in the FAM20C gene have been associated with development of Raine syndrome in humans." (PMID 33195511, 2020).
cancer (2 papers, 2020 to 2023). A tumor composed of atypical neoplastic, often pleomorphic cells that invade other tissues. "Levels of proteins Rngtt, Rp1l1, Tacstd2, Zfyve26, and Zfyve27, which are known to promote a proliferative phenotype in various cancers, were decreased in the brain vasculature of TGF mice, likely as an attempt to attenuate vascular proliferation and remodeling." (PMID 38132326, 2023). "The other 6 genes, GPR98, ZFYVE26, AHNAK2, APOB, ZNF236, and ODZ1, were all supported to be related to cancers by research." (PMID 33244318, 2020).
tumor (2 papers, 2011 to 2024). "Additionally, RT‐qPCR analysis indicated that CHST9 was expressed at low levels in tumour samples, while HMGN4, ITGAV, RAP2A, TMCO3, and ZFYVE26 displayed high expression levels." (PMID 39428564, 2024).
ZFYVE26 also shares sentences with these, for which no sentence is quoted: Parkinsonism (5 papers); Cerebellar atrophy (3); Intellectual disability (3); paraplegia (3); cerebellar ataxia (2); Dystonia (2); spastic ataxia (2); Alexander disease (1); Angelman syndrome (1); Argininemia (1); argininosuccinic aciduria (1); ataxia telangiectasia (1); Atrophy (1); autosomal recessive cerebellar ataxia (1); Autosomal recessive spastic ataxia of Charlevoix-Saguenay (1); axonal motor neuropathy (1); Brain atrophy (1); developmental delay (1); eye movement disorder (1); Friedreich ataxia (1); giant axonal neuropathy (1); hearing loss (1); Hereditary spastic paraplegia type 15 (1); holocarboxylase synthetase deficiency (1); incontinence (1); intellectual disability syndrome (1); juvenile neuronal ceroid lipofuscinosis (1); lysosomal storage disorders (1); movement disorder (1); multiple sclerosis (1).
A further 16 diseases each share a sentence with ZFYVE26 in 1 paper.